HMCN2 (hemicentin 2)
Synonyms: DKFZp434P0216; FLJ23816
Tractability: Antibody: UniProt places it where antibodies can reach, with medium confidence; UniProt predicts a signal peptide or a membrane-spanning region; its Gene Ontology location is reachable by antibodies, with medium confidence.
Gene: Protein-coding gene on chromosome 9 (130,265,760 to 130,434,123, forward strand). Ensembl gene ENSG00000148357.
Subcellular location: Secreted, extracellular space, extracellular matrix; Cleavage furrow
Subcellular location (Human Protein Atlas): Vesicles; Predicted to be secreted
Gene Ontology:
Molecular function: axon guidance receptor activity; extracellular matrix structural constituent; calcium ion binding
Biological process: homophilic cell-cell adhesion; synapse organization; axon guidance
Cellular component: extracellular matrix; axon; neuronal cell body; non-collagenous component of basement membrane; non-collagenous component of interstitial matrix; plasma membrane; basement membrane; cell cortex; cell junction; cleavage furrow; extracellular region
Genetic constraint (gnomAD): Loss-of-function variants: 235 observed, 278.82 expected, observed/expected ratio (o/e) 0.84, 90% interval 0.76 to 0.94. The upper end of that interval is the gene's LOEUF score, 0.94, which puts it in group 3 of 6, group 1 being the genes least tolerant of losing a copy. Missense variants: 3,369 observed, 3,825.7 expected, observed/expected ratio (o/e) 0.88, 90% interval 0.86 to 0.91. Synonymous variants: 1,522 observed, 1,652.4 expected, observed/expected ratio (o/e) 0.92, 90% interval 0.88 to 0.96.
Homologues: Orthologues: chimpanzee HMCN2 (99% identical), macaque HMCN2 (94% identical), pig HMCN2 (84% identical), rat Hmcn2 (81% identical), mouse Hmcn2 (81% identical), guinea pig HMCN2 (79% identical), dog HMCN2 (24% identical). Paralogues in human: IGSF10 (9% identical), MXRA5 (9% identical), DSCAML1 (7% identical), DSCAM (6% identical), SDK1 (5% identical), SDK2 (5% identical), ROBO1 (5% identical), ROBO3 (5% identical), ROBO2 (5% identical), IGSF9B (4% identical), PTPRQ (4% identical), DCC (4% identical), and 24 more.
Diseases named in the same sentence as HMCN2 in open-access papers:
HMCN2 is named in the same sentence as 6 diseases in open-access papers, as found by Europe PMC text mining. Sharing a sentence is not in itself a finding about the gene and the disease. The quoted sentences say what the papers report.
breast carcinoma (1 paper, 2021). "As GALNTL5, MLIP, HMCN2, LRRN4CL and DUOX2 were identified as cytotoxicity-associated genes, we next investigated their effects on therapeutic response by analyzing RNA-seq data and drug sensitivity of multiple breast cancer cell lines using Pearson coefficient analysis." (PMID 35046993, 2021). "(F-J) Survival analysis was performed for GALNTL5, MLIP, HMCN2, LRRN4CL and DUOX2 using log-rank test for RNA-seq data and the corresponding survival data from the TCGA cohort of patients with breast cancer." (PMID 35046993, 2021).
Fraser syndrome (1 paper, 2021). Fraser syndrome is a rare clinical entity including as main characteristics cryptophthalmos and syndactyly. "The generation of mutant Hmcn1 and Hmcn2 knock-in mouse models or the transgenic overexpression of mutant Hmcn1 and Hmcn2 variants may allow to test whether such dominant negative effects of mutant Hemicentins may phenocopy Fraser syndrome-like features in mice." (PMID 34504132, 2021).
tumor (2 papers, 2021 to 2023). "We performed RNA sequencing for 30 pairs of TNBC tissue and matched normal tissue from our hospital, and identified five pivotal genes (GALNTL5, MLIP, HMCN2, LRRN4CL, and DUOX2), which were correlated with associated with CD8+ T cell infiltration, tumor progression and therapeutic efficacy." (PMID 35046993, 2021). "The expression levels of TLL1, HMCN2, FREM2 and MMP17 were significantly higher in normal ovarian tissues than in tumour tissues." (PMID 37388244, 2023).
cardiac disease (1 paper, 2019). "MYBPC3, TTN and SCN5A are established cardiac disease genes, but SH3BGR and HMCN2 are not." (PMID 31641117, 2019).
HMCN2 also shares sentences with these, for which no sentence is quoted: cancer (3 papers); aortic aneurysm (1).